ANK1 (ankyrin 1)
Description:
Component of the ankyrin-1 complex, a multiprotein complex involved in the stability and shape of the erythrocyte membrane. Attaches integral membrane proteins to cytoskeletal elements; binds to the erythrocyte membrane protein band 4.2, to Na-K ATPase, to the lymphocyte membrane protein GP85, and to the cytoskeletal proteins fodrin, tubulin, vimentin and desmin. Erythrocyte ankyrins also link spectrin (beta chain) to the cytoplasmic domain of the erythrocytes anion exchange protein; they retain most or all of these binding functions. [Isoform Mu17]: Together with obscurin in skeletal muscle may provide a molecular link between the sarcoplasmic reticulum and myofibrils.
Synonyms: ANK; SPH1; SPH2; ankyrin-1
Tractability: Small molecule: a structure with a bound ligand is known; it has a high-quality binding pocket. Antibody: its Gene Ontology location is reachable by antibodies, with high confidence. PROTAC: ubiquitination databases record sites on it.
Gene: Protein-coding gene on chromosome 8 (41,653,220 to 41,896,741, reverse strand). Ensembl gene ENSG00000029534.
Subcellular location: Cytoplasm, cytoskeleton (Isoform Er1); Membrane (Isoform Mu17); Cytoplasm, myofibril, sarcomere, M line; Sarcoplasmic reticulum (Isoform Mu18); Sarcoplasmic reticulum (Isoform Mu19); Sarcoplasmic reticulum (Isoform Mu20)
Pathways (Reactome):
Developmental Biology: CHL1 interactions; Interaction between L1 and Ankyrins; Neurofascin interactions; NrCAM interactions
Vesicle-mediated transport: COPI-mediated anterograde transport
Gene Ontology:
Molecular function: ATPase binding; cytoskeletal anchor activity; enzyme binding; protein binding; protein phosphatase binding; spectrin binding; structural constituent of cytoskeleton; structural molecule activity; transmembrane transporter binding
Biological process: endoplasmic reticulum to Golgi vesicle-mediated transport; protein localization to plasma membrane; cytoskeleton organization; exocytosis; maintenance of epithelial cell apical/basal polarity; Golgi vesicle transport; protein localization to cell periphery; signal transduction
Cellular component: ankyrin-1 complex; cytoplasmic side of plasma membrane; plasma membrane; spectrin-associated cytoskeleton; basolateral plasma membrane; cytoskeleton; cytosol; neuron projection; A band; axolemma; cell periphery; cytoplasm; M band; membrane; postsynaptic membrane; sarcolemma; sarcoplasmic reticulum; Z disc
Genetic constraint (gnomAD): Loss-of-function variants: 51 observed, 215.25 expected, observed/expected ratio (o/e) 0.24, 90% interval 0.19 to 0.3. The upper end of that interval is the gene's LOEUF score, 0.3, which puts it in group 1 of 6, group 1 being the genes least tolerant of losing a copy. Missense variants: 2,051 observed, 2,587 expected, observed/expected ratio (o/e) 0.79, 90% interval 0.76 to 0.82. Synonymous variants: 967 observed, 1,056.8 expected, observed/expected ratio (o/e) 0.92, 90% interval 0.87 to 0.96.
Gene-disease validity (ClinGen):
ClinGen rates the evidence that ANK1 causes each of these diseases.
hereditary spherocytosis (autosomal dominant): Definitive. Hereditary spherocytosis is a congenital hemolytic anemia with a wide clinical spectrum (from symptom-free carriers to severe hemolysis) characterized by anemia, variable jaundice, splenomegaly and cholelithiasis.
hereditary spherocytosis (autosomal recessive): Limited.
Homologues: Orthologues: chimpanzee ANK1 (98% identical), macaque ANK1 (98% identical), dog ANK1 (93% identical), mouse Ank1 (91% identical), pig ANK1 (89% identical), rat Ank1 (89% identical), guinea pig ANK1 (88% identical), zebrafish ank1a (71% identical), tropical clawed frog ank1 (68% identical), zebrafish ank1b (64% identical), rabbit ANK1 (61% identical), Caenorhabditis elegans unc-44 (45% identical), and 2 more. Paralogues in human: ANK3 (51% identical), ANK2 (51% identical), ASB7 (6% identical).
Diseases named in the same sentence as ANK1 in open-access papers:
ANK1 is named in the same sentence as 113 diseases in open-access papers, as found by Europe PMC text mining. Sharing a sentence is not in itself a finding about the gene and the disease. The quoted sentences say what the papers report.
hereditary spherocytosis (47 papers, 2012 to 2026). "ANK1 is involved in erythrocyte cytoskeleton formation, and contributes to one of the most common causes of hereditary spherocytosis (HS)." (PMID 42257088, 2026). "Identifying this intronic mutation in proximity to the canonical splicing sites of the ANK1 gene enhances our comprehension of the genotype-phenotype correlations in ANK1-associated hereditary spherocytosis." (PMID 38655052, 2024). "Previously, we reported a new missense mutation in the ANK1 gene that correlated with the hereditary spherocytosis phenotype." (PMID 36676098, 2023). "Genetic variants in ANK1 are associated with susceptibility to diabetes, and in the Mendelian disorder hereditary spherocytosis, a type of hemolytic anemia disease that is known to lead to jaundice, enlarged spleen and liver in pediatric patients." (PMID 36737504, 2023). "Mutation of Leu to Arg at position 6 in ANK1 protein is associated with Spherocytosis, while Leu to Ser in INVS impairs its ability to target DVL1 for degradation." (PMID 35056738, 2022). "For example, a case of HHA in a Chinese patient was originally misdiagnosed as thalassemia and ultimately diagnosed as hereditary spherocytosis because of mutations in the ankyrin 1 (ANK1) gene." (PMID 34249106, 2021). "The remaining heterozygote had a normal α globin gene copy number and had co-inherited a mutation in ANK1 gene associated with Hereditary Spherocytosis (HS)." (PMID 31300739, 2019). "An in vivo functional study has also confirmed that a nonsense mutation in ANK1 leads to the development of spherocytosis." (PMID 26107955, 2015). "Mutations in Ank1 have been associated with hereditary spherocytosis (HS), an inherited haemolytic anaemia characterised by rigid spheroid RBCs." (PMID 24688720, 2013). "Ankyrin-1 mutation is the most common cause of hereditary spherocytosis (HS), accounting for approximately 35–65% cases in Northern European populations." (PMID 23934996, 2013). "We have performed an N-ethyl-N-nitrosourea (ENU) mutagenesis screen and have identified a novel dominant (haploinsufficient) mutation in the Ank-1 gene (Ank1MRI23420) of mice displaying hereditary spherocytosis (HS)." (PMID 22723917, 2012). "Laboratory testing results of 17 patients with hereditary spherocytosis caused by ANK1 mutations." (PMID 36816036, 2023). "Mutations of the ANK1 gene identified in 17 patients with hereditary spherocytosis." (PMID 36816036, 2023). "In this case report, 17 children with anemia or spherocytosis caused by mutations of the ANK1 were retrospectively analyzed to explore the clinical and mutational features of HS patients with mutations of the ANK1, thus providing references for clinical treatment and genetic counseling." (PMID 36816036, 2023). "The ANK1 mutation or deletion in the proximal region of 8p11.2 has been linked with spherocytosis." (PMID 35668409, 2022). "Hereditary spherocytosis (HS) is an inherited disorder characterized by anemia, splenomegaly, and spherical-shaped erythrocytes, caused by mutations in erythrocyte membrane Protein Genes (ANK1, SPTB, SLC4A1, SPTA1, and EPB42)." (PMID 33014018, 2020). "of a de novo ANK1 mutation associated to hereditary spherocytosis: a case report." (PMID 30777044, 2019). "The causes of hereditary spherocytosis are mutations in genes that encode red blood cell (RBC) membrane and cytoskeletal proteins, including ankyrin-1, Band 3 (or AE1), α spectrin, β spectrin, and protein 4.2." (PMID 40008208, 2025). "The frameshift p.Leu884GlyfsTer27 variant of ANK1, nonsense p.Trp652Ter variant of the SPTB, and missense p.Arg490Trp variant of PKLR were detected in all four hereditary spherocytosis cases." (PMID 36832257, 2023). "Particularly interesting for us were five genes associated with clinical phenotypes of hereditary spherocytosis (SPTA1, SPTA, SLC4A1, ANK1, and EPB42)." (PMID 36979763, 2023).
hereditary spherocytosis (continued). "The deletion of a short arm fragment on chromosome 8 is a rare cause of Kallmann syndrome and spherocytosis due to deletion of the FGFR1 and ANK1 genes." (PMID 35668409, 2022). "Then, the method was tested on 10 patients with different genetic mutations causing hereditary spherocytosis (SLC4A1, ANK1)." (PMID 33983926, 2021). "Mutations in ANK1 and SPTB have been linked to erythrocyte membrane disorders including hereditary spherocytosis, in which clinically significant iron overload is commonly seen." (PMID 32354332, 2020). "We report a novel mutation in Ank-1 gene, MRI61689, causing a hereditary spherocytosis-like phenotype, with reduced MCV, increased osmotic fragility and reduced deformability." (PMID 27848995, 2016). "Ankyrin-1 protein is a crucial component of the RBC cytoskeletal complex and its deficiency is responsible for the most common type of human hereditary spherocytosis (HS)." (PMID 22723917, 2012). "There was no deletion of the ANK1 gene associated with spherocytosis, consistent with the phenotype." (PMID 35668409, 2022). "Within the subgroup of five patients with hereditary spherocytosis (HS), we identified heterozygous mutations in the Spectrin Beta, Erythrocytic gene (SPTB) in two, and mutations in the Ankyrin 1 (ANK1) membrane protein encoding gene in the remaining three patients." (PMID 29797310, 2018). "Interestingly, patient F2-P1 presented an additional de novo ANK1 VOUS variant, potentially resulting in a mild form of hereditary spherocytosis, which could explain the mild abnormalities observed in the EMA binding test and ektacytometry." (PMID 40869043, 2025). "In addition, a 9-fold decrease was noted in Ankyrin 1 (ANK 1), an erythrocyte membrane protein that is defective in many patients with hereditary spherocytosis, a common hemolytic anemia." (PMID 25729387, 2015). "However, genetic testing by NGS showed no mutations in ANK1, EPB42, SLC4A1, SPTA1, or SBTB genes in this and an additional two patients, thus ruling out hereditary spherocytosis in all studied cases." (PMID 35681698, 2022).
anemia (17 papers, 2012 to 2026). A reduction in the number of red blood cells, the amount of hemoglobin, and/or the volume of packed red blood cells. "Patients with ANK1 gene mutations experienced more severe anemia compared to those with SPTB gene mutations (p = 0.041)." (PMID 41721551, 2026). "Previous research has indicated that patients with ANK1-HS variants in the spectrin-binding domain exhibit the most severe anemia among affected individuals." (PMID 39995895, 2025). "Our findings were inconsistent with a previous study that patients with mutations of the ANK1 in the spectrin binding domain present the most severe anemia." (PMID 36816036, 2023). "It has also been reported that there is more severe anemia and frequent splenectomy in ANK1 mutations compared to SPTB mutations." (PMID 37280519, 2023). "It has been reported that patients with ANK1 mutations in the spectrin-binding domain has the most severe anemia compared with others, and several loss-of-function mutations in the ZU5 subdomain have previously been reported." (PMID 33868383, 2021). "Patients with ANK1 mutations had more severe anemia than those with SPTB mutations (significantly lower RBC, HB, MCHC, and HCT)." (PMID 33868383, 2021). "Our genotype-phenotypic association study showed that ANK1-HS was more severe than SPTB-HS in anemia." (PMID 33868383, 2021). "This suggested that patients with ANK1 mutations had more severe anemia than those with SPTB mutations." (PMID 33868383, 2021). "The results confirmed that the anemia degree of HS patients caused by ANK1 was more serious than that of patients with SPTB deficiency." (PMID 33868383, 2021). "Several cases of Ank-1 mutations in both human and mice have been reported in the literature and all of them have been associated with a HS phenotype exhibiting anaemia, splenomegaly, and a higher osmotic fragility in RBCs." (PMID 22723917, 2012). "The data we included suggest that children with ANK1 gene mutation have more severe anemia than those with SPTB gene mutation, which may lead to earlier treatment of children with ANK1 gene mutation and younger age of onset." (PMID 40909430, 2025). "To determine the role of neuronal AnkR and confirm its high expression in interneurons, we constructed a floxed allele for Ank1 (Ank1F/F); this new model allows for an exploration of AnkR function in the brain while avoiding the confound of anemia due to loss of AnkR from red blood cells." (PMID 34180393, 2021). "The Ank1 mutation is clearly associated with anaemia and elevated RBC turnover." (PMID 24688720, 2013). "The study found that children with ANK1-HS had significantly more severe anemia than those with SPTB-HS." (PMID 40909430, 2025). "After excluding potential influencing factors such as splenectomy, the anemia symptoms in ANK1-HS patients were more severe than those in SPTB-HS patients." (PMID 40909430, 2025). "The results confirmed that HS patients with ANK1 defects diagnosed in childhood experience more severe anemia compared to those with SPTB defects." (PMID 39044243, 2024). "This indicates that ANK1-HS patients have more severe anemia phenotype compared to SPTB-HS patients." (PMID 39044243, 2024). "This suggests that the anemia phenotype is more severe in pediatric ANK1-HS patients compared to pediatric SPTB-HS patients." (PMID 39044243, 2024). "ANK1-HS patients exhibited more severe anemia compared to cases with SPTB-HS, showing lower levels of RBC and HB (P < 0.05)." (PMID 39044243, 2024). "During infection, both wild-type and Ank1+/Ity16 heterozygous mice developed a mild anemia although the Ank1+/Ity16 heterozygous mice still presented higher RBC counts compared to control mice." (PMID 23390527, 2013). "Defects in ankyrin-1 have been found in >50% of cases of HS in humans, characterised by evidence of haemolysis with anaemia, spherocytic RBC, reticulocytosis, jaundice, gallstones and splenomegaly." (PMID 24688720, 2013).
anemia (continued). "In a cohort of 25 Korean HS patients, anemia was most severe in the ANK1 spectrin-binding domain." (PMID 33014018, 2020). "When two Ank-1(MRI96570/+) G2 progeny were intercrossed, Ank-1(MRI96570/MRI96570) mice were born with severe jaundice and died within several days of birth, suggesting that homozygosity for the Ank-1(MRI96570) mutation caused lethal anemia." (PMID 28751503, 2017). "Heterozygous Ank1+/Ity16 mice were also more susceptible to Salmonella infection although to a lesser extent than Ank1Ity16/Ity16 and they did not inherently present anemia and splenomegaly." (PMID 23390527, 2013). "However, in patients under 14 years of age, ANK1-HS had more severe anemia compared to SPTB-HS, which may be related to the relatively small number of children in previous studies." (PMID 39044243, 2024). "Previous studies have shown more severe anemia and a higher rate of splenectomy in ANK1-HS than SPTB-HS, suggesting that ANK1-HS manifests more severe hemolysis." (PMID 37280519, 2023). "The severity of anemia in Ank1Ity16/Ity16 mutant mice and other ENU-induced Ank1 mutants (Ank1RBC2 and Ank1E924X) was similar with hematocrit levels varying between 22–27%." (PMID 23390527, 2013). "Clinically, Ank1+/Ity16 mice did not present any sign of anemia or splenomegaly." (PMID 23390527, 2013). "The phenotype observed in Ank1+/Ity16 mice may correspond to the human mild form of HS where patients have compensated hemolysis without anemia." (PMID 23390527, 2013).
Alzheimer disease (15 papers, 2014 to 2025). A progressive, neurodegenerative disease characterized by loss of function and death of nerve cells in several areas of the brain leading to loss of cognitive function such as memory and language. "ANK1 has also been linked to Alzheimer’s disease through epigenetic deregulation and appears to play a role in immunomodulation." (PMID 38177348, 2024). "A number of epigenome-wide association studies in Alzheimer’s disease patients consistently report neuropathology-associated DNA hypermethylation of ANK1." (PMID 34180393, 2021). "Recent epigenetic association studies have identified a new gene, ANK1, in the pathogenesis of Alzheimer’s disease (AD)." (PMID 28700589, 2017). "Of these 7, genome-wide studies have associated RIT2 and ANK1 with Parkinson’s and Alzheimer’s disease respectively." (PMID 25493648, 2014). "The ankyrin 1 (ANK1) gene, whose product links integral membrane proteins to the spectrin-actin cytoskeleton, was associated with susceptibility for developing Alzheimer’s disease (AD) and hypermethylation of ANK1 was observed in AD as well as in Parkinson’s disease (PD)." (PMID 34884540, 2021). "Here, we show decreased levels of the H3K4me3 modification in regions of the ANK1 gene in the entorhinal cortex of Alzheimer's disease brain samples, which is a marker of active gene expression." (PMID 33815817, 2021). "We use chromatin immunoprecipitation-qPCR to quantify tri-methylation at histone 3 lysine 4 (H3K4me3) and 27 (H3K27me3) in the ANK1 gene in entorhinal cortex from donors with high (n = 59) or low (n = 29) Alzheimer's disease pathology." (PMID 33815817, 2021). "Several studies have now reported increased DNA methylation in the ANK1 gene in Alzheimer's disease brain samples." (PMID 33815817, 2021). "This study further supports a role for epigenetic modifications in the ANK1 gene in Alzheimer's disease pathology." (PMID 33815817, 2021). "Our study suggests that the ANK1 gene shows altered epigenetic marks indicative of reduced gene activation in Alzheimer's disease." (PMID 33815817, 2021). "Several epigenome-wide association studies of DNA methylation have highlighted altered DNA methylation in the ANK1 gene in Alzheimer's disease (AD) brain samples." (PMID 33815817, 2021). "Two more sites were used as controls: one within the prion gene (PRNP) and another within ANK1, a gene whose hypermethylation has consistently been reported in Alzheimer’s disease (AD)." (PMID 32918118, 2020). "We demonstrate that previous estimates of DNA hypermethylation in ANK1 in Alzheimer’s disease were underestimates as it is confounded by hypohydroxymethylation." (PMID 30898171, 2019). "Recent studies of human brain homogenates have identified hypermethylation of the ANK1 gene in Alzheimer’s disease." (PMID 28700589, 2017). "We note that Ras-Like without CAAX 2 (RIT2) has been recently associated with PD in two large genomic studies and Ankyrin 1, erythrocytic (ANK1) shows altered methylation and expression in Alzheimer’s disease." (PMID 25493648, 2014). "Additionally, several studies have demonstrated that ANK1 showed differential methylation in Alzheimer’s disease (AD) and the cortical ANK1 hypermethylation closely correlated with the presence of AD neuropathology." (PMID 36672967, 2023). "Methylome profiling implicates hypermethylation of Ank1 in Alzheimer’s disease." (PMID 35237591, 2022).